JUND (JunD proto-oncogene, AP-1 transcription factor subunit)
Diseases named in the same sentence as JUND in open-access papers (continued):
Sharing a sentence is not in itself a finding about the gene and the disease.
tumor (continued). "As expected, tumors derived from JKP cells showed increased levels of JunD protein alongside loss of c-Jun immunostaining, and JKP tumor–bearing mice succumbed earlier than KP mice." (PMID 34236045, 2021). "The JNK pathway also promotes cancer cell survival via autophagy involving Bcl-2, tumour immune evasion, compensatory cell proliferation, and interaction with other signaling components such as NF-κB, p38, and JunD." (PMID 34867402, 2021). "Unexpectedly, we found that c-Jun acts as a tumor suppressor in the lung, while JunD is crucial for Ras-driven lung tumor formation." (PMID 34236045, 2021). "In a follow-up study investigating the ∆9-THC antiproliferative mechanism, exposure to ∆9-THC upregulated JunD expression, a proto-oncogene which belongs to the AP-1 transcription factor family, in the tumour cells." (PMID 34259916, 2021). "Consistent with JunD as a key effector of JNK, JunD levels were increased in correlation with the increased tumor burden in c-Junfl/fl; lsl-Jnkk2-Jnk1; lsl-K-RasG12D lungs, with positive staining for phospho-JunD Ser100." (PMID 34236045, 2021). "Overall, these results support a tumor-suppressive role for c-Jun in the lung and demonstrate that JunD is required for Ras-driven lung tumorigenesis." (PMID 34236045, 2021). "JunD heterozygous mice expressing K-RasG12D in the lung also showed a significantly reduced tumor burden compared with JunD-proficient controls, suggesting that JunD plays a driving role in K-RasG12D–induced tumorigenesis." (PMID 34236045, 2021). "We observed that MEN1 and JunD inhibition with MI503 gave rise to significantly accelerated tumor growth, compared to the control treatment." (PMID 34446068, 2021). "While the expression of the AP-1 transcription factor family member cJun was reduced in tumors compared with adjacent non-tumor tissue, the closely related family members JunB and JunD were significantly upregulated." (PMID 33738287, 2021). "JunD has been primarily thought of as a growth suppressor only because menin, a broadly expressed tumor suppressor, inhibits JunD transcriptional activity by interacting with its N-terminal domain." (PMID 31915026, 2020). "Surprisingly, SP1 and JUND deregulated in precancerous and tumor livers of both sexes represent nodules with most protein–protein associations linked to hepatocarcinogenesis." (PMID 33182326, 2020). "In general, c-JUN acts as an oncogenic driver, whereas JUNB and JUND have tumour suppressive effects." (PMID 29597249, 2018). "We recently uncovered an additional mechanism used by HBZ to turn JunD from a growth suppressor to a tumor promoter." (PMID 29379481, 2017). "In situ examination of tumor tissues for expression of JunB, JunD, and c‐Fos by immunohistochemical analysis also confirmed presence of the AP‐1 members but their expression varied in HPV‐positive and HPV‐negative tissues on case to case basis." (PMID 28155253, 2017). "Among the genes in the target list, we focused on JunD which is an AP-1 component and a key mediator of tumor cell proliferation, metastasis and chemoresistance in a variety of tumors." (PMID 27184257, 2016). "It functions as a tumor suppressor gene and interacts with several transcription factors like JUND, NFKB, SMAD3 etc.." (PMID 26307114, 2015). "A higher participation of JunD only in HPV16+ve cells indicates that JunD facilitates tumor differentiation leading to better prognosis." (PMID 26581505, 2015). "On the other hand, participation of JunD observed specifically in HPV16+ve cases appears to induce tumor differentiation as majority of the HPV+ve cases were found to have well differentiated tumors (WDSCCs) that show better prognosis." (PMID 26581505, 2015). "Activation of AhR regulates the activation of the mitogen-activated protein kinase or JunD, which is critically involved in contact inhibitor, inflammation, oncogenic events and tumor progression." (PMID 25226618, 2014).
tumor (continued). "SH3KBP1 has been implicated in cell death and shown to mediate down regulation of EGFR, and JUND has been shown to reduce tumor angiogenesis." (PMID 24550933, 2014). "The chronic oxidative stress generated by the inactivation of JunD, has been shown to promote aging and increase tumour development." (PMID 23398888, 2013). "Menin's tumor suppressor involves direct binding to JunD and inhibition of JunD activated transcription." (PMID 21266030, 2011). "It is interesting to note that JunD is primarily a growth suppressor that functions by interacting with the tumor suppressor, menin." (PMID 21994719, 2010). "While a very low or negligible expression of cJun, JunB, JunD, cFos, FosB, Fra-1 and Fra-2 was observed in normal adjacent tissues, the majority of them showed significantly elevated expressions in tumor tissues." (PMID 19758438, 2009). "CDK4 and JUND are examples of genes, where both the gene expression and protein expression is consistently increased in tumours compared to normal urothelium." (PMID 16265353, 2005). "The observed increase of JUND gene expression in tumours was accompanied by increased protein expression." (PMID 16265353, 2005). "The tumor suppressor MEN1 modulates JUND activation by all MAPKs." (PMID 41020863, 2025). "Interestingly, previous studies have shown that HBZ impedes the tumor-suppressive activity of Menin and promotes JunD-mediated leukemogenesis." (PMID 40128849, 2025). "Reduced JunD levels may disrupt its interaction with the tumor suppressor protein menin, impairing menin’s crucial tumor-suppressive function in neuroendocrine tissues, and perhaps leading to the development of aggressive pituitary NETs over time." (PMID 41203869, 2025). "This suggests that in HTLV-1 infection, HBZ, which is differentially localized in MT-2 and SLB-1 cells, may act as a leukemogenic stimulator that inhibits the tumor-suppressive activity of Menin and promotes JunD-mediated leukemogenesis." (PMID 40128849, 2025). "JunD-deficiency-derived ROS elevation enhances HIF-1α accumulation and stimulates the CXCL12/CXCR4 pathway, which activates RhoA-GTPase to promote myofibroblast differentiation in TME, facilitating tumor metastasis." (PMID 40847302, 2025). "Notably, TFs such as TP63, FOSL1, and JUND were enriched in tumor-specific enhancer and super-enhancer domains, indicating their crucial role in tumorigenesis." (PMID 41323280, 2025). "On the other hand, Jun can stimulate apoptosis in a range of cancer cell types and play a tumour-suppressing role, for example, in a manner inversely related to JunD or by transcriptional regulation of senescence- and inflammation-associated genes including IL-1β, TNFα, CCL3 and CCL8." (PMID 39859271, 2025). "The authors speculated that the JNK signalling pathway may exert both tumour-promoting and tumour-suppressive effects via JunD and Jun, respectively, and the varying outcomes of JNK signalling in different contexts may be due to balancing between both arms." (PMID 39859271, 2025). "Therefore, although JUND promotes its expression and thus tumor progression, increased JUND expression levels also determine responsiveness to EV." (PMID 41020863, 2025). "Elevated IL-6 levels in patients with mCRPC predict malignant prostate cancer progression and poor outcomes in patients with localized tumors Furthermore, we demonstrated that JunD inhibition results in GADD45α- and γ-dependent induction of cell death and inhibition of tumor growth." (PMID 38674385, 2024). "Interestingly, JunD and β-catenin were necessary for menin’s tumor-suppressive activity in AR-negative cell lines, as knocking down JunD or β-catenin abolished the increased colony formation observed with menin knockdown." (PMID 39336822, 2024). "The repression of JunD activity by menin is critical for its tumor-suppressive functions." (PMID 39594699, 2024).
tumor (continued). "Low-dose decitabine (a DNA demethylation drug) combined with PD-1 inhibitors can promote the expansion and effector function of CD8+ exhausted precursor T cells by maintaining the activity of the AP-1/JunD pathway, thus achieving more potent and durable anti-tumor activity." (PMID 38762484, 2024). "Furthermore, menin can also suppress tumorigenesis of the endocrine pancreas through its interactions with the transcription factors CHES1/FOXN3 and JunD in β-cells and islet tumor cells." (PMID 39336822, 2024). "This suppression of pro-angiogenic gene expression may occur through the known menin-binding partner JunD, which has previously been shown to reduce tumor angiogenesis in subcutaneous tumors formed by Kras mutant MEFs." (PMID 39336822, 2024). "In addition, they also identified the involvement of the cyclin-dependent kinase inhibitor p27 and testin (a tumour-suppressor gene) as candidate targets of JunD." (PMID 34259916, 2021). "Finally, the GSE118904 database indicated that the c-Jun and JunD levels in tumor endothelial cells were higher than those of normal endothelial cells." (PMID 34728626, 2021). "Interestingly, significant increase (p < 0.001) in expressions of PI3K, phospho-JNK (pJNK), phospho-AKT (pAKT) and phospho-JunD (pJunD) were observed in the tumor tissues compared to normal tissues." (PMID 34316331, 2021). "Thus, although c-Jun is tumor suppressive in the context of Ras-driven lung tumorigenesis, JNK signaling appears to be oncogenic, and increased JunD phosphorylation by JNK is a potent tumor promoter in the lung." (PMID 34236045, 2021). "Most notably, when the tumour suppressor Menin interacts with JUND, it inhibits its transcriptional activity, indicating that JUND might be involved in neoplastic growth suppression." (PMID 29597249, 2018). "Furthermore, the effects of JUND on transcription are harder to decipher because this TF has been identified as both an oncogene and a tumour suppressor depending on the cellular context." (PMID 29597249, 2018). "The gradual but distinct increase in JunB protein expression after berberine treatment strongly support the tumor suppressor activity of JunB as it was earlier reported that JunB and JunD can negatively regulate cell proliferation and has an opposite effect on gene expression." (PMID 21496227, 2011). "In addition, HBZ interacts with JunD to activate cellular genes including hTERT, which activates the telomerase in cell mitosis, a critical late event in tumor progression that indicates a role for HBZ in the development and maintenance of leukemic cells." (PMID 21994719, 2010). "We also found the gene expression of JUND altered in high-grade tumours." (PMID 16265353, 2005). "In contrast, these mutations did not have an apparent effect on the menin–JUND interaction, further raising the potential for context-specific regulation that might dictate the tumor-suppressive and oncogenic properties of menin." (PMID 37492626, 2023). "Thus, the ability of iASPP to bind and inhibit JunD activity may contribute to iASPP’s tumor-suppressive function in mutant RAS and inflammation-driven tumorigenesis." (PMID 36261000, 2022). "JUN, FOS, STAT3, JUND and NR2F1 were up-regulated in clusters C2 and C3, leading to tumor progression and immune evasion by influencing target genes HSPA1A, CXCL9 and PDGFR." (PMID 42074110, 2026). "We identified tumor-specific super-enhancer domains (T-SEDs) enriched for key TFs, including TP63, FOSL1, and JUND, and demonstrated that these domains regulate genes critical to oncogenic signaling and proliferation." (PMID 41323280, 2025). "Ultimately, our investigation into JARID1D-mediated signaling within the tumor-bone cell interaction revealed that following JIB-04 treatment, there was upregulation of JARID1D, whereas MAOA and JunD expression were downregulated." (PMID 39816691, 2025).
tumor (continued). "The ChIP assay results further indicated that JARID1D knockdown increased H3K4me3 levels at the JunD promoter, suggesting that JARID1D in tumor cells can directly demethylate and regulate JunD in osteoclasts, thus affecting bone metastasis in PCa." (PMID 39816691, 2025). "In contrast, the ED analysis revealed 204 TFs, with 30 showing substantial tumor-specific TFBS enrichment, including TP63, FOSL1, JUND, JUNB, and KLF5, underscoring their potential roles in tumorigenesis." (PMID 41323280, 2025). "Several tumor-specific TFs were detected within the ED and SED, including TP63, FOSL1, JUND, GRHL2, SNAI2, KLF5, TP73, and SMAD3." (PMID 41323280, 2025). "Conversely, Il1r2−/− tumor cells demonstrated higher specificity for regulons controlled by IRF7, HOXB13, and JUND." (PMID 40767963, 2025). "In the case of SED, 225 TFs were analyzed, with TFBSs of 10 TFs identified as enriched in tumor-specific domains (T-SED), including TP63, SMAD3, JUND, and FOSL1/2." (PMID 41323280, 2025). "We mapped H3K27ac-marked super-enhancers (SEs) via ChIP-seq in HPV+ patient-derived xenografts (PDXs) and normal oropharyngeal mucosa, identifying tumor-specific SE domains (T-SEDs) enriched for transcription factors (TFs) including TP63, FOSL1, and JUND." (PMID 41323280, 2025). "high PLP2+ Tumor EPCs score group highly expressed ATF6, ELF1, ERG and PLAGL1 genes, while low PLP2+ Tumor EPCs score group highly expressed ATF5, TBX21, SPIB, LHX2 and JUND genes." (PMID 38482016, 2024). "OS was negatively correlated with PLP2+ Tumor EPCs score, ERG was significantly negatively correlated with JUND, and most other modeling genes were positively correlated." (PMID 38482016, 2024). "While JUND and JUNB demonstrate tumor-suppressive activity, JUN and FOS frequently display oncogenic characteristics when acting as either tumor suppressors or oncogenes in cancer." (PMID 38674385, 2024). "Cluster 0 expressed several tumour-related transcription factors such as ELK4, CREB1, cJun, JunD, KLF6, ETS-1 and ZNF217." (PMID 38480935, 2024). "In the in vitro tumor cell and T cell coculture system, TCROT-I T cells were sorted and consistent expression alteration of JunD was confirmed by quantitative real-time PCR assay." (PMID 36853831, 2023). "The expression of fibrotic genes EGR1, JUND, KLF2 and TAGLN also decreases in tumour samples (PH4 module)." (PMID 38157373, 2023). "JUND (jun D proto-oncogene) transcription factor regulates genes involved in antioxidant defense, H2O2 metabolism, and tumor angiogenesis." (PMID 34685621, 2021). "As lung tumorigenesis appears to be JunD dependant, we performed RNA-sequencing (RNA-Seq) experiments using primary KP and JKP tumor cells to gain mechanistic insights." (PMID 34236045, 2021). "Subsequently, both tumor tissues of HNSCC patients and arecoline-treated cells showed over expression of and activation of JunD by phosphorylation, along with down regulation of ZO-1." (PMID 34316331, 2021). "AP-1 with JunB and JunD participated with c-Fos & Fra-2 in HPV-positive tumors, whereas, c-Jun was the major binding partners forming the functional AP-1 in HPV-negative tumor." (PMID 33344262, 2020). "EGFR inhibition mimics the dual inhibition of MEK/ERK, effectively targets JunD/RSK3 and reverses the BETi resistance phenotype, again highlighting the potential of anti-EGFR therapies in treating BET-inhibition-resistant tumours." (PMID 31937753, 2020). "RT-qPCR was used to detect the expression of LINC01600, JUND, ZFP36, and ATF3 in tumor tissues of 40 PCa patients collected in our hospital." (PMID 32318351, 2020). "Whilst c-Jun oncoprotein seems to drive proliferation and migration in human cancers, at the same time, there are Jun (JunB and JunD), Fos and ATF proteins that have been suggested to exert tumor suppressor function." (PMID 33202877, 2020). "For example, menin, the product of the tumor-suppressor MEN-1 gene, represses JunD-FL transcriptional activity by interacting through its first 48 amino acids." (PMID 29379481, 2017).
tumor (continued). "Comparison of AP-1 family proteins demonstrated high expression of JunD and c-Fos in HPV positive tumors, but interestingly, Fra-1 expression was extremely low or nil in these tumor tissues." (PMID 19758438, 2009). "Agents targeting the interactions of JUN family members with other TFs, like the JUND-AR-targeting GWARJD10, may provide new tools against JUNB/D-mediated tumor progression and become part of novel targeted therapies of high specificity." (PMID 41020863, 2025). "Furthermore, JIB-04 diminished the expression levels of key metastatic mediators, including MAOA, JunD, and RANKL, within metastatic tumor tissues while activating JARID1D." (PMID 39816691, 2025). "Through a comprehensive workflow combining H3K27ac-ChIP-seq and RNA-seq analyses, we identified critical TFs and tumor-specific super-enhancer domains (T-SEDs) that regulate gene expression in HPV+ HNSCC, such as TP63, SMAD3, FOSL2, JUND, JUNB, KLF5, and TFAP2A." (PMID 41323280, 2025). "Notably, JUND and FOSL2 were consistently found to be significant players in all types of tumor-specific domains." (PMID 41323280, 2025). "SCRIPro could accurately predicts well-known master regulators including SPI1, IRF1, FLI1, and STAT2 for mono/macrophages, GATA3, RUNX3, SMARCA4, JUND, and MYB for T-cells, PAX5, BCL2, and IRF4 for B and tumor B-cells." (PMID 39024032, 2024). "recently found that c-Jun functioned as a tumor suppressor in the lung adenocarcinoma, while JunD was increased in the absence of c-Jun and was critical for Ras-mediated lung tumorigenesis." (PMID 37483616, 2023). "We could show that native HBZ can interact with CBP and JunD both in C5MJ and in the ATL tumor cells, although to different extent." (PMID 26140924, 2015). "Although JUND and JUNB are often credited with similar tumor promoter/suppressor roles regarding the cellular context, the vast majority of published data (including those in cancer of non-prostatic origin) credit JUND/JUNB with opposing roles to c-JUN." (PMID 41020863, 2025). "JUND did not correlate with tumour stage, ARID1A levels, or patient survival." (PMID 39885328, 2025). "Several studies have investigated the role of JUND in PCa; nonetheless, no definite answer has been given on whether its role is mostly oncogenic or tumor suppressing, since there are findings supporting both directions." (PMID 41020863, 2025). "Indeed, both CBP and JunD interaction with HBZ were better detected in C5MJ and ATL-2s than in PH961 cells, and this correlated with the higher amount of HBZ expressed in the first two cells compared to the patient ATL tumor cells." (PMID 26140924, 2015). "Several studies (of prostate and non-prostate origin) converge that JUND, similarly to JUNB, displays both tumor promoter and tumor suppressor activities regarding several factors, including the cancer type, cellular context, and cooperation with other TFs." (PMID 41020863, 2025). "For PD, we identified 115 TFs, TFBSs for three of which were significantly enriched in tumor-specific PDs: FOSL2, JUND, and TFAP2A, whereas no significant enrichment was found in normal-specific PDs." (PMID 41323280, 2025). "In view of the acknowledged proto-oncoprotein of JunD, it is not unreasonable to draw the conclusion that a high level of RNF187 is a promoter of tumor progression." (PMID 29254210, 2017).